PARP1 (poly(ADP-ribose) polymerase 1)
Diseases named in the same sentence as PARP1 in open-access papers (continued):
Sharing a sentence is not in itself a finding about the gene and the disease.
tumor (continued). "Although pADPr levels do not entirely correlate with the levels of PARP-1 protein expression in tumor cell lines, all examined tumor cell lines demonstrated significantly increased pADPr expression compared to normal kidney epithelial cells (NK677)." (PMID 34638458, 2021). "We only found 5 DEGs (BIRP1, PARP1, RFC4, RMI2, and RAD51) had protein expression data in HPA and the results showed that the expression levels of BIRP1, PARP1, RFC4, RMI2, and RAD51 in BRCA tumor tissues were higher than in normal tissues." (PMID 34408776, 2021). "There are many reports on the possible use of PARP-1 expression as a prognostic factor in various neoplasms, in which the severity of the disease does not play a significant role." (PMID 33572586, 2021). "Non-overlapping sensitivity to PARPi and PARGi may seem counter-intuitive, as PARP1/2 and PARG work in concert to repair DNA damage; one might expect that both PARPi and PARGi would be toxic towards tumour cells with defects in DNA damage repair." (PMID 34656146, 2021). "Pamiparib is an investigational, selective, oral poly(ADP-ribose) polymerase 1/2 (PARP1/2) inhibitor that has demonstrated PARP–DNA complex trapping and CNS penetration in preclinical models, as well as preliminary anti-tumor activity in early-phase clinical studies." (PMID 33772633, 2021). "Strikingly, this phenomenon was not seen in the matched primary tumor cells, or in a control oral mucosal epithelial cell line, pointing to specific dysregulation of PARP1 expression that was acquired during tumor recurrence." (PMID 35071239, 2021). "Although it seems clear that PARPi will not achieve the degree of inhibition that can be achieved by genetic deletion of PARP-1 and PARP-2, these inhibitors can affect the T cell compartment, which could compromise the T cell immune response to tumours." (PMID 34885119, 2021). "In response to DNA damage, PARylation occurs, and RNAi-mediated depletion of PARP1 encourages the destruction of BRCA1/2-lacking tumor cells." (PMID 34829741, 2021). "Combinational treatment of RT with HT and PARP1-i will possibly allow for a reduction of cDDP and systemic toxicity, without compromising or even improving tumor control." (PMID 33926008, 2021). "Future studies warrant that in a more personalized tumor-specific environment the combination of PARP and Top1 poisons may benefit patients with tumors expressing high levels of PARP1 and Top1." (PMID 33981998, 2021). "Cisplatin and 5-fluorouracil treatment further augmented PARP1 expression in the recurrent, but not the primary, tumor cells." (PMID 35071239, 2021). "Therefore, we examined poly(ADP-ribose) polymerase 1 (PARP1) and Schlafen-11 (SLFN11) expression in DSRCT tumor tissue and the combination of PARP inhibitor olaparib with the alkylating agent temozolomide (TMZ) in a preclinical DSRCT model." (PMID 32279088, 2020). "Furthermore, targeting the MYC paralog-PARP1-DDR axis via concurrent inhibition of BET and PARP1 resulted in synergistic anti-tumor activity in vitro and in vivo against MYC paralog-driven SCLC cells, but not against MYC paralog-independent SCLC cells." (PMID 33134168, 2020). "For instance, in HR-deficient tumour cells, in the absence of BRCA1/BRCA2, PARP1 inhibition has been shown to have cytotoxic side-effects." (PMID 31940791, 2020). "In vivo, blood half-life, stability, tumor targeting, and PARP1 specificity are essential parameters to understand the tracer behavior, its suitability to help delineate tumor vs. non-tumor tissue, and to identify targeting efficiency." (PMID 32640708, 2020). "PARP1 and SLFN11 expression was observed in 100% and 92% of DSRCT tumor tissues, respectively." (PMID 32279088, 2020). "Moreover, it has been shown recently, that simultaneous inhibition of PARP1 and RAD52 can have a synergistic effect on the tumor cell killing." (PMID 32050645, 2020). "Expression of PARP1 and SLFN11 was assessed in 16 and 12 DSRCT tumor tissue samples, respectively." (PMID 32279088, 2020).
tumor (continued). "In addition, treatment of PARP1-KO Jurkat cells with APO866 resulted in upregulation of 6 powerful antioxidant genes, including CAT and genes known to increase tumor cell survival such SIRT2 and UCP2." (PMID 31803365, 2019). "The presence of HMGA2 enhanced DNA damage‐induced PARP1 activation, suggesting that higher concentrations of PARP1 inhibitor olaparib may be required to block PARP1 activity in HMGA2 expressing tumor cells." (PMID 30289618, 2019). "This study extends our knowledge about the regulation of proline synthesis and tumor progression by transcription factor and its derived lncRNA, and suggests that MZF1‐AS1/PARP1/E2F1 axis may be a therapeutic target for tumors." (PMID 31592410, 2019). "PARP1 has a role in repair of single-stranded DNA breaks, and PARP1 knockout shows no negative phenotype and no increased incidence of tumor formation." (PMID 30400387, 2018). "Cells are able to tolerate HR inhibition equally well in the presence or absence of PARP3, in keeping with the observations that AZD2461, a compound that inhibits PARP1 and PARP2 but not PARP3, effectively causes BRCA-mutated tumour regression." (PMID 29467415, 2018). "In cells with intact HR, DSBs that occur as a result of PARP1 inhibition can be resolved, but in tumour cells lacking HR, PARP1 inhibition leads to persistent DSBs and cell death." (PMID 29757235, 2018). "Given the roles of PARP1, ERCC1, and XPF in the repair of DNA damage, one might expect that increased expression would enhance tumor survival." (PMID 29681762, 2018). "In conclusion, DEA induces tumor cell apoptosis through multiple pathways, including cell cycle arrest, AIF nuclear translocation, PARP-1 cleavage, activation of the Bax/Bcl-2 ratio, caspase-3 activation, and inhibition of the ERK and Akt cytoprotective pathways." (PMID 29220397, 2017). "Importantly, combined treatment with PARP1/2 inhibitor veliparib and CDK12 inhibitor dinaciclib efficiently inhibited tumor growth in a patient-derived xenograft model." (PMID 29090014, 2017). "However, tumours with reduced MMR gene expression also displayed low MPG, OGG1 and PARP1 expression." (PMID 28903334, 2017). "Furthermore, Lig3, Lig1 and PARP1 silencing also significantly blocked protein expression of neuronal developmental and NBL tumor markers (TH, Phox2b, TRKB) in differentiating NCSC-MYCN cells, quantified by Western blot analysis." (PMID 29238067, 2017). "Additionally, the interaction between NF-κB and PARP1 upregulates the level of pro-inflammatory cytokines like tumor necrosis factor α (TNFα) and interleukin 6 (IL6), which will also initiate tumor-promoting inflammation." (PMID 28991194, 2017). "In these tumor cells, HSF1 and PARP1 formed a complex in a manner dependent on PARP13." (PMID 29158484, 2017). "This can include the only clinically prosecuted synthetic lethal pairing where genetic loss of BRCA1/2 leads to sensitivity to PARP1/2 inhibition with Lynparza (Olaparib, AZD2281), since PARP1/2 are not reported to show genetic loss in tumours." (PMID 26781748, 2016). "We observed a strong nuclear expression of PARP1 in FaDu and Cal27 tumor tissue, but not in mouse tongue tissue." (PMID 26808835, 2016). "DNA repair enzyme inhibition (e.g., PARP inhibition) may be prolonged in tumor tissues relative to normal tissues in vivo and recent data suggest that PARP inhibitors can “trap” the PARP1 and PARP2 enzymes at damaged DNA." (PMID 26909338, 2016). "Tumor sections of irradiated and non-irradiated tumors were stained for PARP1 using Immunofluorescence staining at 24 and 48 hours post irradiation." (PMID 26808835, 2016).
tumor (continued). "Several studies confirmed any variations or in absence of PARP-1 gene can lead to errors in DNA repair, genetic instability, and modulation of gene transcription; thus it can enhance tumor development." (PMID 27746584, 2016). "However, although we evaluated the nuclear expression of PARP1, BRCA1, and BRCA2 based on the previous reports, the expression of PARP1, BRCA1, and BRCA2 are seen in both the cytoplasm and nuclei of tumor cells." (PMID 27643881, 2016). "High QUIN levels promote tumour chemo-resistance due to enhanced production of NAD+, a vital substrate for Poly [ADP-ribose] polymerase-1 (PARP-1) activation, which facilitates repair of reactive oxygen species-induced DNA damage and enables cells to recover DNA replication after treatment." (PMID 26646699, 2016). "After the identification of ATMIN and PARP1 as the target of miR-124, we re-used MDA-MB-231 to show restoration of ATMIN and PARP1 expression reverses the DNA repair defect induced by miR-124 overexpression and increases resistance to anti-tumor drugs." (PMID 26115122, 2015). "As compared with controls, PARP-1 inhibition indeed alleviated the disease progression, including decreasing cell infiltration, hepatosplenomegaly, and prolonging survival, for further evidence of PARP-1 inhibition potentiality in tumor therapy." (PMID 26314963, 2015). "FO supplementation did not modify the PARP-1 protein expression in tumor tissue (W 1.03 ± 0.02 vs. WFO 1.08 ± 0.03 vs. WCO 1.04 ± 0.05)." (PMID 26303118, 2015). "Histological sections of orthotopic U251 MG tumors showed a clear delineation of tumor tissue with [131I]-I2-PARPi, but not for mice where PARP1 was saturated with a pre-injection of the non-labeled PARP1 inhibitor Olaparib." (PMID 26337803, 2015). "In summary, these data provide supportive preclinical data that inhibiting topoisomerase I and PARP1 in combination, as was demonstrated with the combination of ABT-888 and CPT-11, may result in synergistic decreases in tumor regression for women with TNBC." (PMID 25774912, 2015). "Mir-182 overexpressing tumor cells were hypersensitive to inhibitors of poly (ADP-ribose) polymerase 1 (PARP1); on the contrary, miR-182 antagonism led to enhanced BRCA-1 levels and induced resistance to PARP1 inhibitors." (PMID 24616890, 2014). "In vivo on mice xenografted RP3 cells, siRNA RET/PTC3-SQ NPs were found to: i) inhibit tumour growth, ii) reduce RET/PTC3 oncogene and oncoprotein expressions, iii) induce cell death (cleavage of both caspase-3 and PARP-1) and iv) partially restore differentiation (decrease of Ki67 marker)." (PMID 24759995, 2014). "Interestingly, when taking into account the tumor stage, patients with more advanced grades (III and IV) showed a significant repression for APE1, OGG1 and PARP-1." (PMID 25268610, 2014). "Nonetheless, the inhibition of PARP itself is not lethal for mammals, and PARP1−/− mice are viable and fertile, even though they manifest accelerated aging and exhibit a higher incidence of tumours compared to wild-type controls." (PMID 24792170, 2014). "Interestingly, taking into account the tumor stage, those patients with a more advanced grade (III and IV) showed a significant repression of APE1, OGG1 and PARP-1." (PMID 25268610, 2014). "Furthermore, PARP-1 has been shown to interact with the E3 ubiquitin ligase, CHFR, a tumor suppressor with an important role in the early mitotic checkpoint." (PMID 24350055, 2013). "The effect of Parp1 ablation was neither mouse nor ES cell-specific, as silencing of PARP1 by short interfering RNA (siRNA) in human CAL51 and DLD1 tumour cells also caused resistance to BMN 673 and olaparib." (PMID 23634208, 2013).
tumor (continued). "Collectively, these studies indicate PARP-1 directly fosters ERK signaling in addition to mediating separate but parallel signaling pathways reinforcing the same end result of increased angiogenesis and metastasis, two tumor-promoting features." (PMID 24350055, 2013). "Poly(ADP-ribose) polymerase (PARP) inhibitors induce apoptosis and tumour CR in EW models, and EWS-FLI1 fusion genes maintain the expression of PARP1, a DNA damage response protein and transcriptional coregulator, thereby enforcing oncogene-dependent sensitivity to PARP-1 inhibition." (PMID 23226965, 2012). "Among p16INK4a-positive tumours, CAF-1/p60, PARP-1 and nestin were only barely detectable." (PMID 22882088, 2012). "In tumours where there is little DNA damage, PARP1 is likely not activated and PARP inhibitors are not going to give any significant clinical benefit." (PMID 24970153, 2012). "Cell growth inhibition assays with Olaparib resulted in differential sensitivity, with IC50 values ranging from 1.4 to 8.4 μM, irrespective of tumor type and PARP1 protein expression." (PMID 22184287, 2011). "Critical to the conduct of the Phase 0 trial was validation of an immunoassay for poly(ADP-ribose) (PAR), the product of PARP1, that was sufficiently sensitive, reproducible, and accurate to measure drug-induced modulation of PAR levels in tumor and PBMC samples under clinically relevant conditions." (PMID 22028822, 2011). "Parp-1-/- mice did not demonstrate an increased incidence of tumor formation after either 4-nitroso-quinoline or 2-amino-3-methylimidazo treatment." (PMID 20196871, 2010). "Considering that PARP-1 inhibition reduces angiogenesis, it is possible that hyperactivated PARP-1 might in part drive tumor angiogenesis and metastasis." (PMID 21176168, 2010). "The anti-tumor drug β-lapachone induces PARP-1 dependent cell death independent of caspases via metabolic starvation." (PMID 21176168, 2010). "Although adequate PARP1 protein is necessary for PARP inhibitor function, it is not clear whether high PARP1 expression increases sensitivity to PARP inhibitors in tumours." (PMID 40977519, 2025). "Our findings provide further support for the notion that SNPs in DNA repair genes, particularly in the XPC and PARP1 genes, may serve as prognostic biomarkers for patients with CCA, and highlight the importance of the DNA repair pathways in modulating tumour biology after surgical resection." (PMID 40833230, 2025). "Moreover, PARP7 is indispensable for the anti-tumor properties of thioparib, as PARP7 KO MC38 cells treated with thioparib exhibit no tumor growth suppression, whereas PARP1 KO tumors remain sensitive." (PMID 40128585, 2025). "The enhancement of apoptosis (increased cleaved caspase 3 and PARP1 levels) and reduction in tumor cell proliferation (decreased Ki67 and proliferating cell nuclear antigen (PCNA) levels) by VSV-S treatment were demonstrated by Western blot analysis of tumor tissues." (PMID 39409870, 2024). "It is possible that Lathyrol may influence the expression of CYP17A1 and PARP1, thereby affecting the synthesis and phosphorylation of AR, then produce negative results to the function and activity of neoplasm cells." (PMID 38965120, 2024). "Therefore, PARP1 as an important member of DNA damage repair and energy metabolism pathway of tumor cells, its specific role and mechanism have not been clarified." (PMID 38907095, 2024). "Although disulfiram combined with copper does not reduce tumor size, it increases PD-L1 expression and blocks T-cell entry by inhibiting PARP1 activity and enhancing Glycogen synthase kinase 3 phosphorylation at Ser9 via the (poly (ADP-ribose) polymerase family, member 1) PARP1 gene." (PMID 38693584, 2024). "Interestingly, PARP-1 knockdown did not impact DNA damage or subcutaneous tumor growth in this model." (PMID 39201718, 2024).
tumor (continued). "Interestingly, the combination of RT either with c-Met or PARP-1 inhibition showed a more pronounced inhibitory effect on tumor growth in comparison with non-irradiated tumors." (PMID 37215708, 2023). "Additionally, it is important to note that the adverse effect of PARP-1 is in part assumed by its high baseline expression in CSCs, but most studies do not study how PARP-1 expression contributes or influences tumour progression during the disease." (PMID 36902215, 2023). "Even though some expressions of PARP-1 are present in normal tissues, this biomarker might not be excluded as a target for molecular imaging, because the density of the nuclei in tumor cells are higher compared to normal tissues." (PMID 36835265, 2023). "Our results also highlight the increasingly recognized role of PARP-1 in transcriptional regulation as a key mechanism of action beyond its role in DDR and identify an unanticipated function for these inhibitors in the activation of the pro-tumorigenic potential of the tumor stroma." (PMID 35545049, 2022). "Therefore, our current investigation also provides insights to establish a foundation to devise new synthetic lethal strategies by combining CHK1 or PARP1 inhibitors with TOP1 inhibitors to counteract WRN and NF‐κB mediated intrinsic tumor resistance in clinical settings." (PMID 35582959, 2022). "However, neither full-length PARP-1 or cleaved PARP-1 levels were significantly changed in tumor tissues." (PMID 33750370, 2021). "As new immunotherapies and targeted therapies are revealed, our findings suggest value in further investigations into a panel of personalized tumor markers, which may include proteins with therapeutic relevance such as FOLR1, KRT19, KLK6, PARP-1, TROP2, and IFNL1." (PMID 34868557, 2021). "Targeted RNA methylation system was applied to confirm that the m6A modifications of PARP1 mRNA could play a critical role in NONO-TFE3 tRCC tumor progression." (PMID 33741027, 2021). "In addition, tumor samples of 96 non-UV AS patients were assessed for PARP1 and SLFN11 expression, showing 89–100% PARP1 positivity and 63–66% cases positive for SLFN11 expression." (PMID 34085099, 2021). "The highest uptake in tumour was observed in PSN-1 xenografts (7.34 ± 1.16%ID/g) and was significantly higher than that in AsPC-1, CFPAC-1 and PANC-1 xenografts (P = 0.0019, 0.0047 and 0.0092, respectively), correlating with higher PARP1 expression levels obtained by Western blot." (PMID 32342268, 2020). "The cited studies also confirm our analyses in which we showed that in tumor cells TRPM2 gene expression is significantly decreased whereas PARP1 and PARP2 expression is significantly increased, which may indicate that TRPM2 gene loses its function in tumor cells." (PMID 32423430, 2020). "In addition, PARG silencing decreased PARP1 and NF-kB expression which influenced DC and T cell fate to promote a more favorable CD4/CD8 ratio which could suppress tumor formation." (PMID 33005627, 2020). "Importantly, irrespective of the mouse model, PARP1 was reliably overexpressed in all tumors and intraoperative delineation of tumor versus normal tissue was consistently possible using PARPi-FL." (PMID 32636416, 2020). "When developing a DNA damage response PET imaging agent and in order to completely understand its target engagement, we hypothesise that non-PARP1 and PARP2 effects should also be considered to understand how tumour uptake of a radiolabelled compound relates to PARP biology." (PMID 32342268, 2020). "A battery of 10 SCLC cell lines were grown as 3D tumor spheroids and treated with eight small molecule inhibitors, two for each target, in order to assess the efficacy of BET or Aurora Kinase inhibition in combination with EZH2 or PARP-1 inhibition on SCLC cells." (PMID 33339368, 2020). "The results presented here suggest that inhibition of PARP1 or of ABL protein kinase 1 may have therapeutic value in tumours lacking functional BAF180." (PMID 30995217, 2019).